FBXO4 (F-box protein 4)
Diseases named in the same sentence as FBXO4 in open-access papers (continued):
Sharing a sentence is not in itself a finding about the gene and the disease.
tumor (continued). "Notably, activation of FBXO4 deregulated EMT and tumor progression, including processes such as cell migration and invasion, and FBXO4 regulated ICAM-1 stability via the ERK pathway." (PMID 29137327, 2017). "Fbxo4 tumour suppressor is part of a SCF E3 ligase which has two known substrates." (PMID 29142209, 2017). "Tumor progression and tumor growth were also affected by the transcriptional modulation of FBXO4." (PMID 29137327, 2017). "Several F‐box containing proteins have been characterized either as tumor suppressors (FBXW8, FBXL3, FBXW8, FBXL3, FBXO1, FBXO4, and FBXO18) or as oncogenes (FBXO5, FBXO9, and SKP2)." (PMID 33822486, 2021). "Bypass of BrafV600E-dependent senescence has only been observed in mice wherein a second tumor suppressor such as p16Ink4A, PTEN, or Fbxo4 has been deleted." (PMID 27977682, 2016). "Western analysis of lysates from frozen HNSCC tumour and adjacent normal tissues revealed Fxr1 elevation in tumour tissues; notably, Fbxo4 levels were reduced relative to normal in four out of six tumours with elevated Fxr1." (PMID 29142209, 2017). "Unlike tumor suppressive E3 ligase such as FBW7 and FBXO4, or oncogenic E3 ligase such as SKP2, β-TRCP (β-TRCP1 and β-TRCP2) displays context-dependent (tumor type or cellular context) functions in tumorigenesis." (PMID 29497989, 2018).
cancer (14 papers, 2013 to 2026). A tumor composed of atypical neoplastic, often pleomorphic cells that invade other tissues. "While c-Myc is not the only target, it represents a key oncogenic driver and potential therapeutic target in cancers with loss of Fbxo4 and accumulation of cytoplasmic hnRNPK." (PMID 36329064, 2022). "Consistent with a substrate relationship, Fxr1 is overexpressed in Fbxo4 knockout cells, tissues and in human cancer cells, harbouring inactivating Fbxo4 mutations." (PMID 29142209, 2017). "Although miR340 appears to be downregulated in various types of cancers, its role and underlying mechanism of action in the ubiquitin-mediated degradation of FBXO4 remained unclear." (PMID 29137327, 2017). "This investigation highlights the role for a SCFFbxo4-hnRNPK pathway that determines cell proliferation and metastasis through regulation of c-Myc protein synthesis and highlights potential therapeutic opportunities associated with cancers harboring loss of Fbxo4." (PMID 36329064, 2022). "Correspondingly, FBXO4 dysfunction can contribute to cyclin D1 overexpression and promote malignance in a large fraction of human cancers like melanoma 131 and esophageal cancer." (PMID 32226545, 2020). "Our findings reveal a molecular basis for cancer therapy through targeting glutaminolysis and mitochondrial respiration in ESCC with dysregulated Fbxo4-cyclin D1 axis as well as cancers resistant to CDK4/6 inhibitors." (PMID 30899002, 2019). "Loss of Fbxo4 directly contributes to Fxr1 overexpression in both normal and cancer cells; likewise, re-introduction of Fbxo4 into HNSCC cells triggers Fxr1-dependent senescence, demonstrating the importance of this regulatory loop." (PMID 29142209, 2017). "We also found that the downregulation of FBXO4 from all the three cell lines decreased the percentage of viable cells, which is not unexpected as FBXO4 has been shown to be involved in the regulation of cancer cell growth." (PMID 39688415, 2025). "Additionally, aberrant expression of FBXO4 has been previously documented in various cancers with accumulation of cyclin D1." (PMID 35272674, 2022). "This review summarizes the gene and protein structure of Fbxo4, the mechanisms of how its expression and activity are regulated, and its substrates, biological functions, and clinicopathological importance in human cancers." (PMID 35565262, 2022). "The patients will be benefited only after the whole picture is depicted concerning how Fbxo4 and its relevant signaling regulate the development and progression of human cancers, because the biological functions of Fbxo4 are mainly correlated with and determined by the activities of its substrates." (PMID 35565262, 2022). "This will help to draw a big picture of Fbxo4 functions under both physiological and pathological conditions that will specifically facilitate the start of a new precise medicine era through targeting Fbxo4 in human cancers." (PMID 35565262, 2022). "FBXO4, an F-box protein with numerous substrates in biologically diverse signaling pathways, has key functions in cancer progression and may be a promising therapeutic target." (PMID 29137327, 2017). "Interestingly, overexpression of FBXO4 decreased the migration and invasive ability of metastatic cancer cells, while knockdown of FBXO4 markedly promoted the migratory and invasive properties in non-metastatic cancer cells in the recovery experiments." (PMID 29137327, 2017). "Additionally, a cancer-derived Fbxo4 mutant, I377M14, was assessed for Fxr1 binding." (PMID 29142209, 2017). "Although not all F-box proteins have good characteristics, many F-box proteins, such as SKP2, FBXW7, FBXO4, and FBXO32, are related to the cancer development and progression and cancer cachexia." (PMID 34950036, 2021). "In contrast, in cancer cells lacking Fbxo4 or/and αB-crystallin, unmodified hnRNPK recruits c-Myc mRNA and supports its efficient translation." (PMID 36329064, 2022).
cancer (continued). "E3 ubiquitin ligases (Mule, SCFβ-TrCP, SCFFBW7, TRIM17, APC/CCdc20, and FBXO4) and deubiquitinases (USP9X, Ku70, USP13, JOSD1, and DUB3) work together to balance MCL1 stability, which has an important role in the chemoresistance of cancer cells." (PMID 33803505, 2021).
infection (1 paper, 2014). The state of being infected such as from the introduction of a foreign agent such as serum, vaccine, antigenic substance or organism. "Infection of shRNAs against eight F-box proteins (FBXL5, FBXW5, FBXO3, FBXO4, FBXO5, FBXO24, FBXO25 and FBXO27) upregulated Snail1 protein levels (at least by 2-fold) compared with parental cells or cells infected with a control shRNA." (PMID 24157836, 2014).
FBXO4 also shares sentences with these, for which no sentence is quoted: gastric cancer (3 papers); histiocytic sarcoma (2); lymphoma (2); sarcoma (2); cervical squamous cell carcinoma (1); cervical tumor (1); colon cancer (1); dendritic cell tumor (1); endocervical adenocarcinoma (1); head and neck cancer (1); hemangioma (1); liver cancer (1); lymphoblastic lymphoma (1); myeloid tumor (1); Nephroblastoma (1); oral cancers (1); rectum adenocarcinoma (1); skin cutaneous melanoma (1); uterine tumor (1); uveal melanoma (1).